SATB1 (SATB homeobox 1)
Diseases named in the same sentence as SATB1 in open-access papers (continued):
Sharing a sentence is not in itself a finding about the gene and the disease.
glioblastoma (4 papers, 2017 to 2024). The most malignant astrocytic tumor (WHO grade IV). "A significant association of SATB1 levels with histological grade and poor survival has been described in low and high grade astrocytoma including glioblastoma." (PMID 28049521, 2017). "While in many tumor entities SATB1 overexpression has been observed and connected to pro-tumorigenic processes, somewhat contradictory evidence exists in brain tumors with regard to SATB1 overexpression in glioblastoma and its association with poorer prognosis and tumor progression." (PMID 28049521, 2017). "While the very profound effect on in N-Cadherin expression connects SATB1 expression with tumor cell motility and invasiveness, it should be noted that in high grade glioblastomas N-Cadherin has been found to be inversely correlated with invasive behavior." (PMID 28049521, 2017). "Based on the heterogeneous situation with regard to SATB1 expression levels in glioblastoma, we screened a set of eight commercially available and well-established glioblastoma cell lines for SATB1 levels." (PMID 28049521, 2017). "For the detailed analysis of the functional relevance and possible therapeutic potential of SATB1 inhibition, we employ transient siRNA-mediated knockdown and comprehensively analyze the cellular and molecular role of SATB1 in glioblastoma." (PMID 28049521, 2017). "Despite opposite findings with regard to SATB1 expression in glioblastoma and tumor grade/prognosis, another study found inhibitory effects of a SATB1 decoy on cell proliferation and invasion." (PMID 28049521, 2017). "In contrast to other tumor entities where SATB1 upregulation as compared to normal tissue has been well established, the situation in glioblastoma appears less clear (see Background)." (PMID 28049521, 2017). "The expression of SATB1 in almost all glioblastoma cell lines provided the basis for subsequent functional studies." (PMID 28049521, 2017). "Taken together, this establishes a SATB1 knockdown effect on two central factors in glioblastoma, EGFR and β-catenin." (PMID 28049521, 2017). "Additionally, the overexpression of miR-7-5p was found capable of inhibiting SATB1 (SATB homeobox 1) and reversing the effects of promoting cell migration and invasion in glioblastoma cells." (PMID 36012357, 2022). "We comprehensively analyze the cellular and molecular role of SATB1 in various glioblastoma cell lines with different SATB1 expression levels, establishing in vitro and in vivo the functional relevance of SATB1 in glioblastoma, and the possible therapeutic potential of SATB1 inhibition." (PMID 28049521, 2017). "Our results demonstrate that SATB1 may represent a promising target molecule in glioblastoma therapy whose inhibition or knockdown affects multiple crucial pathways." (PMID 28049521, 2017). "In glioblastoma (GBM), a subset of tumor ECs, via a Twist1/SATB1-mediated sequential transcriptional activation mechanism, produces osteopontin to promote immunosuppressive macrophage (Mφ) phenotypes that inhibit T cell infiltration and activation." (PMID 39337337, 2024). "Notably, we found proliferation inhibitory effects of SATB1 knockdown in all glioblastoma cell lines tested, thus being independent of initial SATB1 expression levels." (PMID 28049521, 2017). "Indeed, our qRT-PCR screening data presented here do not support the notion of SATB1 overexpression in glioblastoma." (PMID 28049521, 2017).
leukemia (4 papers, 2013 to 2024). A malignant (clonal) hematologic disorder, involving hematopoietic stem cells and characterized by the presence of primitive or atypical myeloid or lymphoid cells in the bone marrow and the blood. "Satb1 has previously been shown to be associated with heightened hematopoietic stem cell (HSC) self-renewal, whereas the role of Tubb2a, Cnn3, Nedd4, and Cand2 in hematopoiesis and/or leukemia is poorly described." (PMID 38555405, 2024). "SATB1 (top seven) plays a critical role in relevantpathways conferring anti-tumour immunity.Lastly, knockdown of ENO2 (top nine) has been associated with a reduction on thesurvival rate of leukaemia cells." (PMID 36124841, 2022). "As expected, progression of leukemia was proved by significant increased tumor weight, suggesting that SATB1 knockdown could increase AML proliferation both in vitro and in vivo." (PMID 31130823, 2019).
melanoma (4 papers, 2014 to 2025). A malignant, usually aggressive tumor composed of atypical, neoplastic melanocytes. "SATB1 regulates chromatin remodelers, and its expression is correlated with proliferation and invasiveness of melanoma cells in vitro and in vivo." (PMID 29963229, 2018). "Many of these genes have previously been implicated in melanoma metastasis and prognosis prediction, including MYC, GPNMB, GAB2, and SATB1." (PMID 25116415, 2014). "In a B78ChOVA melanoma mouse model (GSE201071), Satb1 mRNA expression was preferentially downregulated in tumor-infiltrated exhausted OT-1 T cells at days 4 and 14 compared to naïve and effector T cells." (PMID 41372119, 2025). "A few genes located nearby the most significantly associated SNPs in this study have been described as involved in melanoma tumor biology (CKAP4, ID4, SATB1, and PLEKHA5), but not in melanoma susceptibility." (PMID 29963229, 2018).
non-small cell lung carcinoma (4 papers, 2012 to 2015). A group of at least three distinct histological types of lung cancer, including non-small cell squamous cell carcinoma, adenocarcinoma, and large cell carcinoma. "In one study of non-small cell lung cancer, the loss of SATB1 expression was associated with poor survival, while in another study of the same cancer type, the opposite relationship was proposed, demonstrating the highest level of SATB1 mRNA in metastatic cancers." (PMID 25874491, 2015).
cervical cancer (3 papers, 2021 to 2025). A primary or metastatic malignant neoplasm involving the cervix. "In cervical cancer, high SATB1 expression is associated with poorer survival outcomes." (PMID 40071088, 2025).
epilepsy (3 papers, 2021 to 2026). A brain disorder characterized by episodes of abnormally increased neuronal discharge resulting in transient episodes of sensory or motor neurological dysfunction, or psychic dysfunction. "In the present study, we investigate changes in the expression of circRNAs in mTLE patients and experimental epilepsy, and study one of the deregulated circRNAs, circ_Satb1, in more detail." (PMID 35310884, 2022). "Interestingly, hippocampal expression of circ_Satb1, a circRNA derived from special AT-rich sequence binding protein 1 (SATB1), is decreased in both mTLE patients and in experimental epilepsy." (PMID 35310884, 2022).
influenza (3 papers, 2015 to 2022). An acute viral infection of the respiratory tract, occurring in isolated cases, in epidemics, or in pandemics; it is caused by serologically different strains of viruses (influenzaviruses) designated A, B, and C, has a 3-day incubation period, and usually lasts for 3 to 10 days. "Suppression of the transcription factor SATB1 was also predicted as a novel effect of influenza-mediated immune antagonism, and validated experimentally." (PMID 26272204, 2015). "Application of BETA to genome-wide transcriptional profiling data from human DCs identified SATB1 as a novel effect of influenza antagonism." (PMID 26272204, 2015). "We observed that older adults who developed immune responses to influenza vaccine had increased aging signature genes including those targeted by MYC, BATF, and/or SATB1 compared to older adults who were vaccine nonresponders." (PMID 31044512, 2019).
Parkinson disease (3 papers, 2019 to 2025). A progressive degenerative disorder of the central nervous system characterized by loss of dopamine producing neurons in the substantia nigra and the presence of Lewy bodies in the substantia nigra and locus coeruleus. "In Parkinson’s disease patients, SATB1 (a CDKN1A inhibitor) levels are reduced in the substantia nigra, while CDKN2A, MMP3, IL-6, IL-1α, and CXCL8 levels are elevated, indicating an increased aging burden." (PMID 39963130, 2025). "Importantly, the genes SATB1, MIR22HG, and GBA (red stars) are associated with Parkinson's disease." (PMID 38303548, 2024).
psoriasis (3 papers, 2020 to 2025). An autoimmune condition characterized by red, well-delineated plaques with silvery scales that are usually on the extensor surfaces and scalp. "Finally, associations of SNPs of SATB1 with colitis, psoriasis and MS have been linked to SATB1’s role in Treg development in the thymic cortex." (PMID 33537838, 2021). "We also observed an expansion of regulatory T cells in three of five patients with psoriasis, and an additional population of T cells characterized by expression of SESN3, a marker of T cell senescence, SATB1, and FURIN." (PMID 33053333, 2020).
viral infection (3 papers, 2015 to 2024). "We investigated SATB1 protein levels in pediatric and adult donors and assessed expression dynamics of this chromatin organizer across different immune cell subsets in human organs, as well as in antigen‐specific T cells directed against acute and chronic viral infections." (PMID 30803026, 2019). "To examine if these drugs can rescue senescence phenotype independent of virus infection, we used SATB1 knockout (KO) hPSCs, which have been reported to show senescence phenotype when differentiated toward DA neurons." (PMID 38237586, 2024).
acute myeloid leukemia (2 papers, 2019 to 2024). Acute myeloid leukemia (AML) is a group of neoplasms arising from precursor cells committed to the myeloid cell-line differentiation. "To characterize SATB1 mRNA and protein expression in acute myeloid leukemia (AML), we performed qRT-PCR and Western blot on bone marrow mononuclear cells from 52 newly diagnosed AML patients." (PMID 31130823, 2019). "Also, Luo and colleagues concluded that SATB1 can serve as a predictor of a good response to therapy in acute myeloid leukemia (AML)." (PMID 39195213, 2024).
Allergy (2 papers, 2023 to 2025). An allergy is an immune response or reaction to substances that are usually not harmful. "Notable genes associated with allergy, immune responses, and inflammation were found (LCK, BACH2, SATB1, LIME1, KSR1, BCL11B, TCF1, and EVL)." (PMID 41394805, 2025). "This study was not only the first to reveal the possibility of cis-regulatory transcriptional mechanisms that could regulate Satb1 expression in both human and murine T cells, but it was also the first-link SATB1 to allergy and inflammatory disease." (PMID 37193606, 2023).
clear cell renal cell carcinoma (2 papers, 2019 to 2025). "Similarly, in clear cell renal cell carcinoma, elevated SATB1 levels are associated with better OS, a relationship potentially regulated by miR-21-5p, which modulates SATB1 expression." (PMID 40071088, 2025).
colorectal tumors (2 papers, 2014 to 2015). "In most cases of colorectal tumors, we found lower SATB1 mRNA levels in comparison with unchanged colon mucosa." (PMID 25874491, 2015). "The tumor weights from the SATB1-overexpressing cells were approximately 5–6 times heavier than those from the empty vector cells, indicating that SATB1 could promote the growth of colorectal tumors in vivo." (PMID 24971456, 2014).
head and neck squamous cell carcinoma (2 papers, 2020 to 2023). A squamous cell carcinoma that arises from any of the following anatomic sites: lip and oral cavity, nasal cavity, paranasal sinuses, pharynx, larynx, and salivary glands. "Increased levels of SATB1 expression have been linked with metastasis, poor prognosis, and decreased survival rates in head and neck squamous cell carcinoma (HNSCC)." (PMID 38067304, 2023). "In head and neck squamous cell carcinoma (HNSCC), SATB1 upregulation is correlated with TNM classification, metastasis, poor prognosis and reduced overall survival." (PMID 32451408, 2020).
intellectual disabilities (2 papers, 2022 to 2025). "Mutation of the Satb1 gene in rats induced various behavioral deficits that are similar to those observed in people with neurodevelopmental delays, intellectual disabilities, and ASD." (PMID 40571781, 2025). "One such example of this is a recent study which identified 42 individuals with causative variants in the gene SATB1, where individuals presented with a range of neurological symptoms including intellectual disability, developmental delay and motor difficulties." (PMID 35626763, 2022). "Although the described SATB1 syndrome is primarily considered as intellectual disability, language difficulties were observed in 89% of cases." (PMID 35626763, 2022).
metastasis (2 papers, 2017). The spread or migration of cancer cells from one part of the body (where they first appeared) to another. "Among patients with GIN, SATB1 overexpression was associated with depth of invasion (T stage: RR 1.27, 95% CI 1.18–1.36, P = 0.000), regional lymph node metastasis (N stage: RR 1.51, 95% CI 1.22–1.87, P = 0.000), and distant metastasis (M stage: RR 2.54, 95% CI 1.46–4.41, P = 0.001)." (PMID 28636989, 2017).
metastatic cancers (2 papers, 2015 to 2019). A carcinoma which has spread from the original site of growth to another anatomic site. "For TGFB3 and SATB1 this difference is small, with the genes repositioned in ∼33.3% (5/15 and 6/16 respectively; false negative rate ∼66.7%) of non-metastatic cancers and 16.7% (1/6) of metastatic cancers." (PMID 31681438, 2019).
mycosis fungoides (2 papers, 2024). Classical mycosis fungoides is the most common type of mycosis fungoides (MF), a form of cutaneous T-cell lymphoma, and is characterized by slow progression from patches to more infiltrated plaques and eventually to tumors. "Many studies have shown that loss of SATB1 expression is linked to the progression of mycosis fungoides, and moderate to high SATB1 expression is associated with a better prognosis in cutaneous T-cell lymphoma." (PMID 39195213, 2024). "A low SATB1 mRNA expression level was related to an unfavorable prognosis in human mycosis fungoides and revealed decreased eosinophil infiltration, increased large-cell transformation, a high Ki-67 index, and elevated PD-1 expression." (PMID 39176397, 2024). "Previous studies conducted in Mycosis fungoides and Sézary syndrome have shown that SATB1 can influence the expression of IL5 and IL9." (PMID 39195213, 2024).
neuroblastoma (2 papers, 2016 to 2024). Neuroblastoma (NB) is the most common solid, extracranial childhood tumor. "To validate our hypothesis that miR22‐3p mediates the decrease in GCase upon SATB1 removal, we performed functional assays in the DA‐like SK‐N‐MC human neuroblastoma cell line." (PMID 38303548, 2024).
Sepsis (2 papers, 2016 to 2024). Sepsis is defined as life-threatening organ dysfunction caused by a dysregulated host response to infection. "We identified significant upregulation of NTSR1, BCL6, ZDHHC19, MGLL, and ALPK1 in sepsis compared to healthy individuals, while VAV2 and SATB1 were significantly downregulated in sepsis." (PMID 38167131, 2024). "While SATB1’s specific link to systemic inflammation and sepsis is limited, its role in modulating immune responses affects pro-inflammatory and anti-inflammatory pathways." (PMID 38167131, 2024). "The observed significant upregulation of NTSR1, BCL6, ZDHHC19, MGLL, and ALPK1 in sepsis compared to healthy individuals, along with the notable downregulation of VAV2 and SATB1 in sepsis, provides a comprehensive picture of the altered gene expression landscape during sepsis." (PMID 38167131, 2024). "Additionally, bulk RNA analysis revealed significant increases in NTSR1, BCL6, ZDHHC19, MGLL, and ALPK1 in sepsis, and significant decreases in VAV2 and SATB1 in sepsis; FCHO1 showed a significant decrease in sepsis patients who did not survive compared to those who survived at 28 days." (PMID 38167131, 2024).
T-cell lymphoma (2 papers, 2015 to 2021). "Of the six significantly mutated genes identified in Bx T-cell lymphomas with MuSiC analysis, only one, SATB1, is reported mutated among the Gr T-cell lymphoma tumors." (PMID 26377837, 2015).
adult T cell leukemia (1 paper, 2024). "One study previously reported reduced expression of SATB1 in adult T cell leukemia (ATL), which could increase Jurkat cell invasiveness through the activation of the Wnt/β-catenin signaling pathway." (PMID 39195213, 2024).
anaplastic large cell lymphoma (1 paper, 2024). Anaplastic large cell lymphoma (ALCL) is a rare and aggressive peripheral T-cell non-Hodgkin lymphoma, belonging to the group of CD30-positive lymphoproliferative disorders, which affects lymph nodes and extranodal sites. "Specifically, CD30 expression is limited to three hematologic diseases including cHL, anaplastic large cell lymphomas (ALCLs), and primary cutaneous CD30+ T-cell lymphoproliferative disorders in which SATB1 expression is associated with a better prognosis." (PMID 39195213, 2024).
Anxiety (1 paper, 2021). Intense feelings of nervousness, tension, or panic often arise in response to interpersonal stresses. "Mice with Satb1 knockout are marked by anti-anxiety behavior in the open field test." (PMID 34073140, 2021).
astrocytoma (1 paper, 2017). "SATB1 expression was positively correlated with astrocytoma pathological grade, while a negative correlation with patients’ overall survival was found." (PMID 28049521, 2017).
autism (1 paper, 2025). Persistent deficits in social interaction and communication and interaction as well as a markedly restricted repertoire of activity and interest as well as repetitive patterns of behavior. "In support of our results here, haploinsufficiency of SATB1 itself has been reported to cause an autism-like neurodevelopmental condition." (PMID 40612695, 2025).
Barrett esophagus (1 paper, 2014). Esophageal lesion lined with columnar metaplastic epithelium which is flat or villiform. "We have examined the expression of SATB1 in matched normal squamous epithelium, normal gastric mucosa, Barrett’s esophagus, gastric intestinal metaplasia, and primary and metastatic adenocarcinoma in patients with cancer of the upper gastrointestinal tract with known clinical outcome." (PMID 25326863, 2014).
choriocarcinoma (1 paper, 2022). An aggressive malignant tumor arising from trophoblastic cells. "The SATB1 suppression was also confirmed in in vivo studies using mice bearing JEC-3 choriocarcinoma, with ~80% and ~30% for targeted and untargeted liposomes, respectively." (PMID 35456655, 2022).
chronic hepatitis B (1 paper, 2016). "Immunohistochemical (IHC) staining was used to investigate SATB1 expression in liver tissues from chronic hepatitis B (CHB) and liver cirrhosis (LC) in HBV-infected patients." (PMID 27883059, 2016).
chronic obstructive pulmonary disease (1 paper, 2022). A chronic and progressive lung disorder characterized by the loss of elasticity of the bronchial tree and the air sacs, destruction of the air sacs wall, thickening of the bronchial wall, and mucous accumulation in the bronchial tree. "A microRNA-21-mediated SATB1/S100A9/NF-κB axis has been reported to promote chronic obstructive pulmonary disease pathogenesis." (PMID 35935235, 2022).
cognitive decline (1 paper, 2023).
cutaneous T-cell lymphomas (1 paper, 2024). "Wang and colleagues demonstrated SATB1 deficiency in Sezary syndrome, an aggressive leukemic variant of cutaneous T-cell lymphoma (CTCL) involved in apoptosis resistance in tumor cells." (PMID 39195213, 2024). "On the other hand, in a previous study, SATB1 was considered an oncogene in CD30+ cutaneous T-cell lymphomas because its activity was directed towards silencing p21." (PMID 39195213, 2024).